DDR1 (discoidin domain receptor tyrosine kinase 1)
Diseases named in the same sentence as DDR1 in open-access papers (continued):
Sharing a sentence is not in itself a finding about the gene and the disease.
ovarian cancer (continued). "The DDR1 expression level in the ovarian cancer tissue samples was increased 6.7 fold on average compared with normal ovarian tissue." (PMID 21541037, 2011). "Three PTKs, janus kinase 1, insulin-like growth factor 1 receptor, and discoidin domain receptor 1 (DDR1), were identified and only DDR1 was overexpressed in all ovarian cancer tissues examined for the validation by quantitative real-time PCR." (PMID 21541037, 2011). "Elevated levels of DDR1 protein expression appear to be highly predictive of the presence of ovarian cancer." (PMID 21541037, 2011). "Further investigation of DDR1 as a clinical biomarker and as a therapeutic target is warranted, especially for ovarian cancer." (PMID 21541037, 2011). "In summary, we have identified DDR1 as a differentially overexpressed PTK in ovarian cancer tissue using a combination of cDNA subtraction and degenerate PCR-based cloning." (PMID 21541037, 2011). "Regarding cisplatin resistance in ovarian cancer, Deng and colleagues revealed miR-199a-3p as an upstream regulator of Discoidin Domain Receptor Tyrosine 1 (DDR1) (which confers the malignance and cisplatin resistance of ovarian cancer) that happens to be hypermethylated in ovarian cancer." (PMID 34298969, 2021). "Similarly, in epithelial ovarian cancer, a decrease in DDR1 expression is observed during the EMT process due to CpG hypermethylation of its promoter, and DDR1 inhibition did not affect E-cadherin expression at the protein level." (PMID 33917302, 2021). "Interestingly, previous findings suggested that hypermethylation-dependent silencing of miR-199a-3p directly regulates the expression of DDR1 in ovarian cancer." (PMID 33365310, 2020). "Therefore, we investigated the involvement of miR-199a-3p and DDR1 in regulating cisplatin sensitivity in ovarian cancer cells." (PMID 28743276, 2017). "However, based on our results which were limited to in vitro phenotypes, the effects of miR-199a-3p and DDR1 on ovarian cancer metastasis in vivo still remain unverified." (PMID 28743276, 2017). "Interestingly, knockdown of DNA methyltransferase 3A (DNMT3A) notably increased miR-199a-3p level and then attenuated the expression of DDR1 in ovarian cancer cells, which suggested that DNMT3A was responsible for the miR-199a promoter hypermethylation." (PMID 28743276, 2017). "So we want to elucidate whether silencing miR-199a-3p promotes the malignant phenotypes of ovarian cancer via induction of DDR1." (PMID 28743276, 2017). "Hence, the downstream factors or pathways of DDR1, which are responsible for ovarian cancer development, are worth investigating in the future." (PMID 28743276, 2017). "Contrast with DDR1, miR-199a-3p was dramatically downregulated in ovarian cancer tissues." (PMID 28743276, 2017). "Furthermore, deprivation of DNMT3A restored the expression of miR-199a-3p and resulted in a reduced DDR1 expression in ovarian cancer cells." (PMID 28743276, 2017). "However, in cancer, DDR1 induces tumor metastasis via promoting cell migration and invasion, which is also observed in our study for ovarian cancer." (PMID 28743276, 2017). "Therefore, our study indicates that aberrant methylation status in ovarian cancer breaks the inhibitory effect of miR-199a-3p on DDR1 expression and consequently promotes the malignant phenotypes of ovarian cancer." (PMID 28743276, 2017). "Therefore, more investigations are needed to explore the potential of miR-199a-3p and DDR1 as novel therapeutic targets for ovarian cancer." (PMID 28743276, 2017). "Moreover, expression of DDR1 is known to be dysregulated in multiple human cancers such as lung, breast, hepatic, and ovary cancers, suggesting a previously unappreciated role of DDR1 in tumor formation and progression." (PMID 26297342, 2015). "These inhibitors of DDR1 may prove to be therapeutically beneficial for the treatment of advanced ovarian cancer." (PMID 21541037, 2011).
ovarian cancer (continued). "DDR1 was more highly expressed in ovarian cancer samples compared with normal ovarian tissues." (PMID 21541037, 2011). "Although its functional role and clinical utility remain to be examined in future studies, our results suggest that the expression of DDR1 may serve as both a potential biomarker and a molecular target for advanced ovarian cancer." (PMID 21541037, 2011). "However, the precise mechanisms underlying the abnormal expression of DDR1 in ovarian cancer has not been well investigated in previous studies." (PMID 28743276, 2017). "However, the molecular mechanism underlying the abnormal expression of DDR1 in ovarian cancer was not well investigated in the previous studies." (PMID 28743276, 2017). "Other transcripts that were upregulated during ovarian cancer spheroids formation include DACH1, the Discoidin domain receptor (DDR1), the winged helix transcription factor Forkhead box P1 (FOXP1), and MUC1." (PMID 37189618, 2023). "With the upregulated expression of miR-199a-5p in ST09 treated PA1 cells, and its inverse correlation with DDR1 in ovarian cancers, we examined the protein expression of DDR1 in both ST09 treated PA1 and A2780 ovarian cancer cell lines." (PMID 34837026, 2021). "This notion of switching between DDR1 and DDR2 has been recently suggested in ovarian cancer, where DDR2 mRNA expression is low in epithelial-like cells and increases in mesenchymal-like cells." (PMID 33917302, 2021). "The ST09-treated ovarian cancer lines showed decreased NF-κB expression and COX2 transcript levels, indicating the miR-199a-5p: DDR1 axis to be involved." (PMID 34837026, 2021). "While we have focused here on DDR1 and DDR2 in breast and ovarian cancer, they are increasingly important and relevant anti-cancer targets for multiple tumor types." (PMID 34805157, 2021). "Like DDR1, DDR2 is involved in the modulation of MMP expression in ovarian cancer where it regulates the expression of MMP1–3, 7, and 13 mRNAs and the activity of MMP2 and MT1-MMP." (PMID 33917302, 2021). "COL4A6 may promote tumor aggressiveness and chemoresistance via the E2F/DDR1 axis, and COL4A6 expression can predict clinical outcomes in patients with ovarian cancer." (PMID 40603853, 2025). "Therefore, to understand the ST09 mediated effects on the downstream DDR1 pathways, we analysed the expression of these mediators in both PA1 and A2780 ovarian cancer cell lines treated with increasing concentrations of ST09 for 48 h." (PMID 34837026, 2021). "Thus, as a consequence of DDR1 downregulation upon ST09 treatment, we evaluated the expressions of these MMPs in both ovarian cancer cell lines." (PMID 34837026, 2021). "In this work, a negative correlation between DDR1 and a tumor suppressor miRNA, miR-199a-3p, was observed in ovarian cancer tissues." (PMID 28743276, 2017). "No DDR1 staining was present in epithelial cells in normal ovary and serous adenoma, but the expression was increased in the ovarian cancer cells." (PMID 21541037, 2011). "Although it would be nonspecific for ovarian cancer (because it could also indicate various other malignancies), the levels of DDR1 expression in body fluid or serum may have clinical prognostic utility as a biomarker for cancer." (PMID 21541037, 2011). "The DDR1 gene was overexpressed in all eight individuals, whereas the expression levels of JAK1 and IGF1-R were not increased in half of the ovarian cancer tissue samples." (PMID 21541037, 2011).
melanoma (26 papers, 2019 to 2026). A malignant, usually aggressive tumor composed of atypical, neoplastic melanocytes. "Kindlin-3 is a tumor suppressor protein involved in focal adhesion, whose expression in melanoma patients is associated with better survival and DDR1 expression." (PMID 41492134, 2026). "An elevated expression of DDR1 in melanomas is associated with a poor prognosis and the downregulation of DDR1 inhibits the migration, invasion and survival of melanoma cells." (PMID 34830178, 2021). "Elevated expression of DDR1 is associated with reduced survival in colorectal cancer, mediates chemoresistance in hepatocellular carcinoma, and correlates with poor prognosis in melanoma, increased invasiveness in gastric cancer, and metastasis in lung cancer." (PMID 40563472, 2025). "Additionally, they associated DDR1/2 expression with melanoma progression and with the invasive and therapy-resistant phenotype." (PMID 35936735, 2022). "Interestingly, a significant fraction of melanomas was found to be associated with an amplification of DNA copy number and higher mRNA levels of DDR1 and DDR2 (respectively 13% and 10% of samples)." (PMID 34957688, 2022). "Fibroblast-derived ECM protects melanoma cells from BRAFV600-targeted therapies by inducing DDR1 and DDR2 linear clustering." (PMID 41492134, 2026). "In BRAF-mutant melanoma cells, an interaction between DDR1 and intβ1, regulated by Kindlin-3, has been observed." (PMID 41492134, 2026). "Here, using both loss-of-function and gain-of-function approaches, we show that ABL1/2 and DDR1 are critical nodes during NRAS-mutant melanoma intrinsic and acquired MEK inhibitor (MEKi) resistance." (PMID 36765910, 2023). "Analysis of TCGA databases showed that a significant fraction of melanoma cells strongly expressed DDR1 and DDR2." (PMID 37174072, 2023). "Accordingly, melanoma cells at the IF of human primary tumours showed lower levels of DDR1, MFN2 and OPA1, while harbouring higher levels of pAMPK and higher amoeboid score." (PMID 37217519, 2023). "The authors noticed a high expression of DDR1 and DDR2 in melanoma that was associated with a bad prognosis." (PMID 35936735, 2022). "Consistently, interaction of melanoma cells with CAFs’ ECMs induces activation and linear clustering of DDR1/2." (PMID 35936735, 2022). "In patient‐derived short‐term melanoma cultures, higher DDR1 and DDR2 protein levels were detected in BRAF mutant MM099 and MM029 and NRAS mutant MM165 cells with the MITFlow, SOX10low, and AXLhigh de‐differentiated phenotype signature." (PMID 34957688, 2022). "A recent study correlated high DDR1 expression in melanoma lesions with poor prognosis and showed that DDR1 controls melanoma cell invasion and survival." (PMID 34957688, 2022). "Functionally, inhibition of DDR1/2 expression or activity overcome ECM-mediated melanoma cell resistance to the targeted therapy in vitro." (PMID 35936735, 2022). "In particular, DDR1/DDR2 induces matrix-mediated drug resistance to MAPKi via activation of the pro-survival NIK/IKKα/NFκB2 pathway in melanoma cells." (PMID 34067929, 2021). "Our functional in vitro studies also showed a key role for DDR1 in melanoma cell proliferation, migration, invasion, and survival." (PMID 33014862, 2020). "Because DDRs are crucial regulators of tumor cell behavior in response to their immediate microenvironment and in light of our recent data on DDR1 in melanoma, we propose that DDR1 targeting in melanomas resistant to MAPK inhibitors is worth exploring." (PMID 33014862, 2020). "While suppression of DDR1 has also been observed to reduce the invasive properties of other cancer cell lines such as melanoma, colon and hepatoma cells." (PMID 32492656, 2020). "In this review, we will focus on DDR1 and melanoma, and its potential role in promoting malignant features and as a potential target to overcome drug resistance." (PMID 33014862, 2020).
melanoma (continued). "Analyses of skin samples harboring melanoma showed a strong expression of DDR1 in the melanoma cells, which was positively correlated with invasive depth and patient survival." (PMID 33014862, 2020). "In addition, a DDR tyrosine kinase inhibitor (DDR1-IN-1) also significantly suppressed the proliferation of melanoma cell line M10 in vitro and in C8161 and SKMEL5 xenograft tumor models in vivo." (PMID 39594665, 2024). "In summary, these exciting data indicate that targeting ABL1/2 and DDR1 in combination with MEKi may be an effective therapeutic regimen for patients with aggressive NRAS-driven melanomas, who have a poor prognosis and limited therapeutic options." (PMID 36765910, 2023). "Importantly, we observe that the adhesion receptor DDR1 and mitochondrial fusion proteins are down-regulated in invasive areas of human melanoma tissues while there is an increase in AMPK and Myosin II activity." (PMID 37217519, 2023). "Interestingly, DDR1/DDR2 clustering on the collagen-rich matrix is increased upon melanoma cell treatment with BRAFi." (PMID 34067929, 2021). "Furthermore, it has been reported that MAF-derived matrix enriched of fibrillar and non-fibrillar collagens promotes the clustering of the collagen receptors DDR1/DDR2 into linear membrane structures in melanoma cells." (PMID 34067929, 2021). "To further examine the association between DDR1 and melanoma, we analyzed a curated set of seven non-redundant cutaneous melanoma cohorts from the cBioPortal site." (PMID 33014862, 2020). "We previously reported that DDR1 is expressed in melanomas, where it can promote tumor malignancy in mouse models of melanoma, and thus, DDR1 could be a promising target to overcome drug resistance." (PMID 33014862, 2020). "The application of siRNA against DDR1 and DDR2 suppressed migration, invasion, and survival in human melanoma cell lines." (PMID 39594665, 2024). "This group has reported that targeting DDR1 and DDR2 was able to overcome collagen matrix-mediated tumor cell resistance to BRAF-targeted therapy in melanoma." (PMID 37174072, 2023). "For instance, DDR1 expression was positively correlated with hypoxia, stemness, and angiogenesis in renal cell carcinoma (RCC) and metastasis in melanoma (MEL), while negatively correlated with DNA damage in glioma." (PMID 37031216, 2023). "As such, lower levels of DDR1, MFN2 and OPA1 and higher levels of pAMPK and higher amoeboid scores were also found at the IF of human melanoma metastatic lesions." (PMID 37217519, 2023). "The same group also showed that discoidin domain receptors DDR1 and DDR2, which are type I collagen receptors, are able to impact the melanoma cell phenotype." (PMID 37174072, 2023). "In human A375 melanoma, HT29 colon carcinoma and SK-HEP hepatoma cells, chemical inhibition or silencing of DDR1 reduces cell adhesion to collagen I and MMP-dependent invasion." (PMID 35205677, 2022). "Here, we show that DDR1 and DDR2 are key mediators of MMDR in melanoma, through the pro‐survival non‐canonical NF‐κB2 pathway." (PMID 34957688, 2022). "We next examined the levels of DDR1 and DDR2 in a collection of melanoma cell lines and short‐term melanoma cultures in relation to the cell state differentiation markers MITF, SOX10, and AXL." (PMID 34957688, 2022). "This matrix-mediated drug resistance was demonstrated to be DDR1 and DDR2 dependent and promoted melanoma cell survival via the NIK/IKKα/NF-κB2 signaling pathway." (PMID 36119516, 2022). "In line with this notion, we found that DNA amplification and elevated mRNA levels of DDR1 negatively correlated to the activity of BRAF and MEK inhibitors in melanoma cell lines from the GDSC (Genomic of Drug Sensitivity in Cancer)." (PMID 34957688, 2022). "DDR1 and DDR2 are both expressed at different levels in the skin, particularly in the epidermis from which melanoma originates following the malignant transformation of melanocytes." (PMID 34957688, 2022).
melanoma (continued). "Overlapping functions have been attributed to DDR1 and DDR2 in melanoma with regard to cancer cell growth and invasiveness." (PMID 34957688, 2022). "The analysis of TCGA datasets for cutaneous melanoma showed that the DDR1 and DDR2 genes were genetically altered in 20% and 13% of melanoma cases, respectively." (PMID 34957688, 2022). "Because melanoma and stromal cells also express DDR2, these preclinical studies with DDR1-IN-1 suggest that DDR1, and possibly DDR2, constitutes a potentially new target in melanoma." (PMID 33014862, 2020). "The enhanced expression of DDR1 and DDR2 collagen receptors in melanoma cells was observed when grown on 3D decellularized ECM from melanoma-related CAFs, in contrast to matrices from regular dermal fibroblasts, highlighting the tumor-enhancing function of CAF-derived ECM." (PMID 40430018, 2025). "These exciting data indicate that drugs targeting ABL1/2 and DDR1, many of which are FDA-approved, may be effective in conjunction with MEKi for patients with NRAS-mutant melanomas, a notoriously hard-to-treat class of patients." (PMID 36765910, 2023). "Thus, cotargeting ABL1/2 and DDR1 not only prevents ERK activation of downstream targets but also impacts other pathways involved in proliferation, survival, and melanoma progression." (PMID 36765910, 2023). "Another approach might be to disrupt ECM fiber linearization in the melanoma TME by targeting the YAP mechanotransduction pathway and DDR1/2-dependent collagen signaling using Verteporfin and Imatinib, respectively." (PMID 36119516, 2022). "Thus, the data in this study provide the rationale for testing the use of drugs targeting ABL1/2 and DDR1 in combination with MEKi for patients with NRAS-mutant melanomas who have failed to respond to immunotherapy." (PMID 36765910, 2023). "Thus, DDR1 is activated in SK-MEL-2MR and SK-MEL-30MR, in the absence of external collagen stimulation, likely due to collagen upregulation and secretion by the melanoma cells themselves." (PMID 36765910, 2023). "Since a number of ABL1/2 and DDR1 inhibitors are FDA-approved for treating leukemia, these data may pave the way for testing their clinical efficacy in combination with MEK for treatment-refractory NRAS-driven melanomas." (PMID 36765910, 2023). "Moreover, to date, the contribution of DDR1 to NRAS-driven melanoma growth and MEKi resistance has not been investigated." (PMID 36765910, 2023). "Conversely, negative survival Z-scores in melanoma, renal, and TNBC cohorts indicate that low DDR1 expression correlates with improved ICB outcomes, highlighting tumor-type specificity." (PMID 40869052, 2025). "DDR1 and DDR2 were both expressed in melanoma cell lines regardless of their differentiation of cell phenotype." (PMID 34957688, 2022).